BRAF (B-Raf proto-oncogene, serine/threonine kinase)
Diseases named in the same sentence as BRAF in open-access papers (continued):
Sharing a sentence is not in itself a finding about the gene and the disease.
tumor (continued). "All 758 differentially methylated loci in BRAF-mutated primary tumor samples from this study were analysed in the cell line DNA methylation dataset." (PMID 28931069, 2017). "High nuclear RBM3 expression was statistically significant associated with BRAF wild type tumours, and RBM3 expression was significantly higher in patients who underwent secondary surgery and received irinotecan based treatment." (PMID 28800641, 2017). "Jovanovic’s report showed that among papillary thyroid microcarcinomas with multiple tumor foci, 83% had genetic alterations consistent with monoclonal origin based on genome-wide allelotyping and BRAF mutation analysis." (PMID 29070029, 2017). "In single case reports, ATC patients with BRAF V600E mutated tumours were treated with a BRAF-inhibitor." (PMID 28489587, 2017). "The original BRAF-associated methylation loci were identified in a set of 20 paired tumor and normal tissues using Agilent 244k human CpG island microarrays." (PMID 28931069, 2017). "In the identified BRAF-mutation-like subtype group, 50% of tumours were known BRAF mutants, and 50% were BRAF wild-type." (PMID 29479053, 2017). "Application of sensitive genetic methods (qPCR, next-generation sequencing (NGS), MassARRAY, or pyrosequencing) and IHC has demonstrated that there is considerable heterogeneity in the presence of the BRAF p.V600E mutation in populations of PTC tumor cells." (PMID 28636673, 2017). "Within these 57 BRAF mutated tumours, 16 are microsatellite instable tumors (MSI), 7 are microsatellite stable tumors (MSS) and 34 tumors do not have MSI/MSS status available." (PMID 29479053, 2017). "To identify cellular changes accompanying increased tumor take rate and the increased BRAF mutation, we performed IHC staining of PDOX tumors." (PMID 29152094, 2017). "Since the discovery of BRAF mutations, efforts have been underway to understand the mechanisms by which these mutations lead to cancer progression, and to identify potential therapeutic strategies to target BRAF mutation positive tumours." (PMID 28282860, 2017). "The association of high RBM3 expression with BRAF wild type tumours is in accordance with earlier reports." (PMID 28800641, 2017). "Therapeutic choices should be personalized based on multiple factors: BRAF mutational status, comorbidities, tumor burden, and immune status." (PMID 29179523, 2017). "CIMP-H tumours, defined as tumours with hypermethylation at >3/5 marker genes, are significantly associated with mutations in BRAF, female patients and location in the proximal colon." (PMID 28351398, 2017). "In conclusion, RAS mutations in serum, and BRAF mutation in serum combined with pMMR in tumor were strong independent prognostic factors in patients with RAS/RAF mutated tumors." (PMID 28378527, 2017). "From the 22 samples analysed, five KRAS (codon 12 and 13), two BRAF(V600E) and 2 PIK3CA mutants were identified, including one tumour with a BRAF and PIK3CA mutation." (PMID 28931905, 2017). "In the context of tumor cell heterogeneity, it is preferable to use the most sensitive method for BRAF p.V600E mutation detection." (PMID 28636673, 2017). "Two, representing CIMP-H and CIMP-L tumours, were associated with BRAF and KRAS mutations, respectively." (PMID 28351398, 2017). "The TCGA dataset included 37 normal mucosa samples and 203 tumor samples, 25 of which carry a BRAF mutation and 81 a KRAS mutation." (PMID 28931069, 2017). "Multivariate analysis that included RAS, PIK3CA, and BRAF tumor mutations and baseline prognostic variables revealed that liver metastasis, unresectable primary tumor, RAS and BRAF tumor mutations had independent prognostic value for early progression." (PMID 28068936, 2017). "The following five predictors of MSI‐H were identified in the test cohort: female (1 point), mucinous component (2 points), tumor size ≥ 60 mm (2 points), location in proximal colon (3 points), and BRAF mutation (6 points)." (PMID 28544821, 2017).
tumor (continued). "This mutation leads to persistent activation of BRAF, and is affected by increasing tumor progression and changing tumor microenvironment." (PMID 29228722, 2017). "Compared to 28% in patient tumor, BRAF V600E mutant allele frequency increased in xenografts (67%, 70%, and 67% in passage I, II and III, respectively)." (PMID 29152094, 2017). "We examined primary tumor characteristics including ulceration, BRAF mutation status, and Breslow depth in patients who subsequently developed stage IV disease and were treated with ipilimumab at 3 institutions." (PMID 29177235, 2017). "A previous study showed that tumor cells harboring either KRAS/BRAF mutations or EGFR amplification were slightly less sensitive to BEZ235 than other cells." (PMID 29296217, 2017). "Overall, while recent data applying IHC point to intra and inter tumor homogeneity of BRAF-mutated expression, the issue of genetic heterogeneity is still debated." (PMID 28039443, 2017). "This study generally found this to be true, with both CIMP-H tumours being located in the right colon and having BRAF mutations and KRAS wild type." (PMID 28097409, 2017). "Two patients had a BRAF mutation (both c.1799T > A/V600E mutations), and both had tumours located in the right colon." (PMID 28097409, 2017). "Preclinical studies demonstrated that this agent was effective in inhibiting the growth of many tumor cells bearing a BRAF mutation." (PMID 28954413, 2017). "Associations with clinical features, characteristics of the primary culprit tumor, and progression and survival data were assessed based on the mutation status of BRAF and NRAS, revealing the three cohorts BRAF-mutant, NRAS-mutant and WT." (PMID 28797232, 2017). "As such, there are insufficient data to justify the exclusion of patients with a RAS, PIK3CA, or BRAF tumor mutation from Bmab treatment regimens." (PMID 28068936, 2017). "Advanced individual therapy concepts focus on well characterized mutations, e.g. KRAS and BRAF, and thus stress the understanding of tumor biologies for individualized medicine." (PMID 28903393, 2017). "These BRAFV600-mutant patients progressed within 1 year of receiving BRAF inhibitor monotherapy and analysis of the matched pre-treatment and progressing tumours revealed that only the progressing biopsies expressed the BRAF exon 4–8∆ splice variant." (PMID 28503307, 2017). "Since KRAS and BRAF mutations are mutually exclusive, BRAF testing is performed only in KRAS WT tumours." (PMID 29137623, 2017). "The LightCycler PCR method has a limitation because a single base pair change in the BRAF mutation was detectable down to the level of 25% of tumor cells when a homozygous mutant cell line was used as control." (PMID 29132392, 2017). "Tumor size in BRAF-wild-type cases (median = 3.5, range from 1.1 to 6.5) was similar to the BRAF-mutated cases (p=0.71)." (PMID 28903326, 2017). "Yet, a trend towards higher incidence of BRAF mutation was found in patients with higher tumor stage (p = 0.054)." (PMID 28680105, 2017). "Patients with resected CRC had DNA extracted from eight defined tumour areas which were analysed for two genetic mutations (BRAF and KRAS) and one epigenetic trait (CpG island methylator phenotype/CIMP)." (PMID 28097409, 2017). "Compared with EGFR, the detection of BRAF mutation both in tumor tissue and plasma still has a long way to go." (PMID 28572536, 2017). "Data obtained by some authors, including TCGA study indicated on a clonal nature of the BRAF V600E mutation, demonstrating its homogeneous distribution across the tumor." (PMID 28829399, 2017). "Recent studies revealed that BRAF inhibitors exclusively block tumor growth in tumors harbouring BRAFV600E mutations since CRAF can over-compensate for BRAF inhibition." (PMID 28537899, 2017). "CD3+ T cell infiltration of the tumor correlated with good response, whereas the presence of a BRAF or NRAS mutation correlated with poor response, especially in patients pretreated with a BRAF inhibitor." (PMID 29157311, 2017).
tumor (continued). "In the present study, we retrospectively collected clinical data and tumor samples from patients with BRAF-mutated CRC and analyzed their clinicopathologic characteristics." (PMID 29037218, 2017). "Tumour cells with BRAF or KRAS mutations that drive strong activation of ERK1/2 typically become ‘addicted’ to the pathway for proliferation or survival." (PMID 28548464, 2017). "We therefore assessed the relationship between clinicopathologic factors including RAS, PIK3CA, and BRAF tumor mutation status and PFS." (PMID 28068936, 2017). "Using the TST vendor-supplied bioinformatics pipeline we were able to detect and validate by orthogonal methods known activating driver mutations in EGFR, KRAS and BRAF below 5% VAF in cases with ≥10% tumor cell content by routine pathological assessment." (PMID 28415793, 2017). "An additional 4-month exposure to the BRAF inhibitor vemurafenib resulted in a highly drug resistant tumor that showed 3 additional new DNA mutations in the genes BUB1B, PINK1, and COL16A1." (PMID 28173755, 2017). "In vitro xenograft tumor cell cultures also had high BRAF mutation frequencies with 66% (p-4), 69% (p-21) in monolayer and 67% (p-5 and p-21) in neurospheres." (PMID 29152094, 2017). "A trend towards higher incidence of BRAF mutation was found in patients with higher tumor stage (p = 0.054)." (PMID 28680105, 2017). "We also described how mutated BRAF affected tumor angiogenesis and proved that targeting BRAFV600E stabilized the tumor vascular bed and abrogated hypoxia in mouse xenografts." (PMID 29270405, 2017). "BRAF mutations were found in tumours from 14 patients (panitumumab + mFOLFOX6 n = 11; bevacizumab + mFOLFOX6 n = 3), all of whom had RAS WT mCRC." (PMID 28424871, 2017). "Reports have shown that co-targeting CDK 4/6 and BRAF is efficient in BRAF mutated tumours to overcome BRAF-inhibitor resistance." (PMID 28489587, 2017). "In proximal colon cancer, MSI-high and BRAF mutation occurred in relation to many other tumor features, indicating their important roles during carcinogenesis." (PMID 28623901, 2017). "This is an unfortunately frequent occurrence for patients undergoing targeted therapy for tumours harboring the activating V600E mutation of the BRAF gene." (PMID 28282860, 2017). "In fact, 3 of the 5 tumours (60%) that showed a significant anti-proliferative response uniquely at 0.1 μM Selumetinib (Subset 2) had KRAS or BRAF mutations." (PMID 28931905, 2017). "There are reports suggesting more frequent prevalence of impaired BRAF mutation in deficient MMR (dMMR) mCRCs (34.6%) compared to early-stage dMMR tumours (24%)." (PMID 28067827, 2017). "For these analyses, we evaluated the basal and on-treatment cfDNA status of the four patients in our cohort who carried a prior to treatment tumor mutation in BRAF or BRAF/PIK3CA." (PMID 27852040, 2017). "New combinations with MAPK and PI3K pathway inhibitors are needed in tumours with mutated KRAS or BRAF, which are exclusive." (PMID 28106826, 2017). "It is possible that HERV-K Env expression is part of the mechanism used by the tumours to escape the treatment against mutated BRAF by re-activating the ERK1/2 pathway." (PMID 28651004, 2017). "If we accept that tumor formation occurs over years in most cases, then the rapid and almost universal acquisition of resistance to inhibitors of the BRAF V600E mutation is suggestive that this is indeed occurring." (PMID 28441401, 2017). "Only three patients had KRAS, NRAS or BRAF mutations, which we were able to follow in cfDNA and BM-derived tumour DNA during the course of trametinib therapy to evaluate the subclonal response to treatment." (PMID 28492226, 2017). "DNA was extracted from FFPE tumor tissues and BRAF mutation status (wild-type/mutation) was successfully established in 98% of the samples." (PMID 28125730, 2017).
tumor (continued). "The first blinded prospective multicenter study compared the mutation status of KRAS and BRAF in CRC tumor tissue, using routine gold-standard methods, and in ctDNA, using a quantitative PCR-based method." (PMID 28903450, 2017). "The specificity on FFPE sample 79.2% suggests that 20.8% (51 out of 245) of BRAF wild-type tumors in this dataset share the same gene expression pattern as BRAF-mutated tumours." (PMID 29479053, 2017). "In this study using the subset of TCGA-SKCM samples filtered by estimated tumor purity, BRAF and NRAS mutations were found to occur in a mutually exclusive pattern." (PMID 29383127, 2017). "CastPCR was applied to detect BRAF mutations in tumor tissues and 6.5% (7/107) patients were identified as mutation positive, consistent to the result concluded by NGS." (PMID 28572536, 2017). "While BRAF V600E mutation appears to play a critical role in tumor initiation, its expression during tumor progression remains controversial." (PMID 28039443, 2017). "The BRAF V600E mutation is able to promote tumor cell proliferation and survival by constitutive activation of the mitogen-activated protein kinase (MAPK) signaling pathway." (PMID 28002810, 2017). "Further, the 2016 ESMO guidelines state that for patients who are candidates for therapies that maximize tumor shrinkage or for those with BRAF mutations, the cytotoxic triplet FOLFOXIRI plus Bev is an option." (PMID 28977949, 2017). "Since 3635PXA patient tumor contained 13% normal diploid cells, the corrected BRAF V600E mutation rate increased from 28% to 32.18% (i.e., 28/87=32.18%), it is still much lower than that in the xenograft tumors (>67%)." (PMID 29152094, 2017). "Seventeen percent (4/24) of patients with stage I disease and a mutation in tumor also had a RAS/BRAF mutation in the serum." (PMID 28378527, 2017). "As an example, the mutational status of BRAF was found to be different between different sites of the primary tumor (intratumor heterogeneity), between the primary tumor and metastases, and between several metastases from the same patient." (PMID 28484715, 2017). "The current predictive model identified five predictors by multivariate logistic regression analysis: BRAF mutation, female sex, location in the proximal colon, and tumor size ≥ 60 mm; will be available as a result of routine medical treatment." (PMID 28544821, 2017). "A RAS/BRAF tumor mutation was detected in 64.5%, and mutated DNA was found in the serum of 42.3% of these patients." (PMID 28378527, 2017). "The ORRs of patients with a PIK3CA or BRAF tumor mutation were very low (28.6%), and more than 40% of patients with a BRAF tumor mutation had confirmed disease progression at the first evaluation." (PMID 28068936, 2017). "BRAF mutation in the serum and proficient mismatch repair (pMMR) protein in tumor also indicated significantly worse prognosis, OS (HR = 3.45, 95% CI = 1.52–7.85, P = 0.0032) and DFS (HR = 3.61, 95% CI = 1.70–7.67, P = 0.0008)." (PMID 28378527, 2017). "As PTEN has been previously implicated in resistance to BRAF inhibitors, we first examined the mutation status and expression of this tumor suppressor." (PMID 27655717, 2016). "A total of 204 adult DTC samples (Age >18 years) were analyzed for mutations in exon 15 of the BRAF gene by performing polymerase chain reaction (PCR) amplification of tumor genomic DNAs and direct sequencing of amplicons using Sanger sequencing." (PMID 27387551, 2016).
tumor (continued). "Age <45 years, multifocality, familiality, male sex, aggressive pathological variants, BRAF V600 mutation and tumor size larger than 1 cm are the main independent preoperative variables." (PMID 27185169, 2016). "Along the same line, the group of Erik Sahai has discovered a complex and dynamic cross-talk between tumor cells, tumor associated host cells and proteins of the tumor matrix in the context of therapy-resistant BRAF-mutant melanoma cells." (PMID 27854331, 2016). "CMS1 comprised 14 % of the patients and classified older, female patients with hypermutated MSI tumours demonstrating BRAF mutation and immune activation." (PMID 27340376, 2016). "Mutations in BRAF gene have been documented to be involved in malignant transformation of tumor tissue." (PMID 27099668, 2016). "Mutations previously known in selected tumour probes such as cKIT (P10721.1, L576P; Mel8) and BRAF (P15056.1, V600E; Mel16) were detected by this analysis." (PMID 27869121, 2016). "Most importantly, P19bT tumor contains a BRAF (V600E) mutation, providing resistance towards the targeted drugs." (PMID 27845624, 2016). "Single cell clone sequencing from the cell culture generated from this treatment resistant tumor revealed the co-occurrence of a BRAF and NRAS mutation in a single cell." (PMID 27791198, 2016). "In the present study, we also assessed the association between DNA methylation status and clinicopathological features, including tumor locations in early colorectal lesions with BRAF mutation." (PMID 27145369, 2016). "The presence of BRAF gene mutation is associated with sensitivity of tumor cells to BRAF inhibitors (vemurafenib, dabrafenib)." (PMID 25902737, 2016). "The results showed that higher percentages of BRAF mutant alleles were associated with poor prognostic factors such as older age, larger tumor size, ETE, and higher recurrence rate." (PMID 27410688, 2016). "KRAS, NRAS and BRAF mutations were detected in two or all three tumor types while mutations in EGFR were uniquely detected in NSCLC." (PMID 27101000, 2016). "HER2‐overexpression was associated with KRAS/BRAF wild‐type (WT) status at all stages: in 5.2% WT versus 1.0% mutated tumours (p < 0.0001) in stage IV and 2.1% versus 0.2% in stage II–III tumours (p = 0.01), respectively." (PMID 26690310, 2016). "Age and tumor stage were adjusted for in the multivariate analysis of most studies, but BRAF mutation, KRAS mutation, and microsatellite instability (MSI) were assessed as confounding variables only in a few studies." (PMID 26941852, 2016). "In all disease stages, but particularly in stage IV, we observed a significant association of HER2 overexpression with KRAS/BRAF WT tumours (p < 0.0001)." (PMID 26690310, 2016). "All patients had a BRAF V600E or K somatic tumor mutation and all underwent lumbar puncture (LP) because of suspected central nervous system (CNS) involvement on the basis of neurological symptoms, MRI imaging, or both." (PMID 27863426, 2016). "The identified BRAF p.K483E mutation in the patient’s tumor is localized to the BRAF kinase domain and is predicted to be deleterious by Polyphen, SIFT, and PROVEAN." (PMID 27799065, 2016). "In 50% of cutaneous melanomas, activating mutations in BRAF drive tumor survival and proliferation through ERK activation." (PMID 27028853, 2016). "Tissue from the primary tumor was tested for BRAF status, revealing the presence of the V600E mutation." (PMID 27520988, 2016). "Lower CCDC67 expression was significantly associated with aggressive tumor behaviors, such as advanced tumor stages and lymph node metastasis, as well as BRAF mutation." (PMID 26716505, 2016). "Several studies have shown that dual treatment with selective inhibitors of PI3K/Akt and BRAF is associated with a synergistic tumor growth inhibition in mutated CRC cell lines presenting primary resistance to a BRAF inhibitor." (PMID 27102434, 2016).